NRG1 (neuregulin 1)
Diseases named in the same sentence as NRG1 in open-access papers (continued):
Sharing a sentence is not in itself a finding about the gene and the disease.
schizophrenia (continued). "Neuregulin 1, first identified as a schizophrenia risk gene, is a trophic factor containing EGF (epidermal growth factor)-like domain." (PMID 31780806, 2019). "Previous studies showed that injection of anti- Nrg1 antibodies led to the appearance of schizophrenia-like phenotypes in mice, which is likely caused by elevated Nrg1 signaling." (PMID 31653237, 2019). "Given the strong association of Nrg1 with schizophrenia, most studies have focused on the neurodevelopmental role of Nrg1 signaling in the formation of cortical circuits." (PMID 31583038, 2019). "Single nucleotide polymorphisms in NRG1; have been associated with psychosis and enlarged lateral ventricles and white matter disruption in schizophrenia." (PMID 30319362, 2018). "First, NRG1 was identified as a schizophrenia candidate gene in a large-scale genetic association study." (PMID 29520222, 2018). "Mutations in high-risk gene candidates for schizophrenia such as neuregulin 1, DISC1, and dysbindin have all been demonstrated to disturb NMDA receptor regulation." (PMID 29449801, 2018). "Together, these findings indicated that Egr3 was regulated downstream of three proteins independently implicated in schizophrenia risk: NMDARs, NRG1 and CN." (PMID 29520222, 2018). "Both NRG1 and its receptor ErbB4 have been genetically linked to schizophrenia, and ErbB4 deficient mice display some schizophrenia-related phenotypes." (PMID 29844389, 2018). "Treatment with NRG1 antibodies that block receptor binding caused behavioral alterations associated with schizophrenia, including, hyper-locomotion and impaired pre-pulse inhibition of startle (PPI)." (PMID 29844389, 2018). "Neuregulins have frequently been associated with schizophrenia, as those deficient in NRG1 have fewer working NMDA receptors." (PMID 28729842, 2017). "Amongst the schizophrenia-susceptibility genes with the most prominent TTTPs were those with established synaptic functions, including Rgs4, Snap25, Kalrn, Htr2a and Nrg1." (PMID 28893375, 2017). "Using LD method, the haplotype 221121 of NRG1 and its six SNPs were associated to schizophrenia in Indian population." (PMID 28993723, 2017). "Lines of evidence suggested that gain-off function mutations in Nrg1 are also risk factors for schizophrenia." (PMID 28993723, 2017). "DAOA and NRG1 polymorphisms were shown to predict the transition to schizophrenia in individuals at HR/UHR for psychosis." (PMID 29326614, 2017). "Nrg1 mutants also displayed alterations in lipid metabolism and other metabolic pathways implicated in pathophysiological processes associated with schizophrenia." (PMID 28338897, 2017). "Our results suggest genetic variation at the 5′ and 3′ ends of NRG1 are associated with schizophrenia and provide renewed justification for further investigation of NRG1’s role in the pathophysiology of schizophrenia." (PMID 28094814, 2017). "Studies of candidate schizophrenia risk genes and postmortem analyses have implicated changes in neuregulin 1 (Nrg1) signaling as a contributor to disease-associated endophenotypes." (PMID 28275713, 2017). "A mouse model with a different mutation of Nrg1, a heterozygous mutation in Nrg1 immunoglobulin-like domain (Ig-Nrg1+/-), displayed schizophrenia-like behaviors, particularly suppression of open field, running wheel, and T-maze." (PMID 28993723, 2017). "One study demonstrated the lowest level of PPI in Caucasians and African Americans schizophrenia subjects who also carried the homozygous A allele (NRG1 rs3924999)." (PMID 28993723, 2017). "Other variations or haplotypes located in NRG1 were also associated with schizophrenia using different SNPs tagging, analysis methods, sample size, and populations." (PMID 28993723, 2017). "Our findings from the 5′-end of NRG1 that associate rs62510682, rs35753505 and 478B14-848 with schizophrenia have previously been identified in other meta-analyses." (PMID 28094814, 2017).
schizophrenia (continued). "Variants of NRG1 can be detected genetic association with schizophrenia in different periods and features of patients, which can further confirm these risks to disease." (PMID 28993723, 2017). "As NRG1 plays critical roles in myelination, there is an increase in an attention to the NRG1 gene variant association with neuropathology in patients with schizophrenia." (PMID 28993723, 2017). "NRG1 is considered as a risk gene for schizophrenia, and variants of it are associated with schizophrenia clinical symptoms." (PMID 28993723, 2017). "Mice with disruption of NRG1, a gene associated meta-analytically with risk for schizophrenia, were studied on a proof-of-concept basis." (PMID 29201594, 2017). "Mutant mice with disruption of neuregulin-1, a gene associated meta-analytically with risk for schizophrenia, constitute proof-of-concept studies of murine facial dysmorphology in a manner analogous to clinical studies in schizophrenia." (PMID 29201594, 2017). "Treatment-resistant schizophrenia (TRS) patients represent a considerable subgroup who have significant increases in multiple NRG1 splice variants in peripheral blood." (PMID 29163244, 2017). "Neuregulin 1 (Nrg1) is necessary for the normal development of the heart and nervous system, and its dysregulation is implicated in schizophrenia." (PMID 29230082, 2017). "NRG1 was one of the 108 schizophrenia-associated genes identified in 2014 (Schizophrenia Working Group of the Psychiatric Genomics Consortium, 2014), and it attracted much attention due to its role in regulation of neuronal migration and myelination." (PMID 28993723, 2017). "Of the four neuregulin isoforms described, polymorphisms in the NRG1 gene have been repeatedly associated with schizophrenia." (PMID 28804444, 2017). "Although a number of risk haplotypes along with several genetic polymorphisms in the 5′ and 3′ regions of NRG1 have been linked with schizophrenia, results have been mixed." (PMID 28094814, 2017). "In a study of Northern Swedish Isolated Population, five SNPs located in the second intron of NRG1 were found with schizophrenia association also by LD method." (PMID 28993723, 2017). "Three of the seven HapICE markers (rs62510682, rs35753505 and 478B14-848) at the 5′-end as well as two SNPs (rs2954041 and rs10503929) near the 3′-end of NRG1 showed significant associations with schizophrenia." (PMID 28094814, 2017). "Altered neuregulin 1 (Nrg1)/ErbB signaling and glutamatergic hypofunction have been implicated in the pathophysiology of schizophrenia." (PMID 28275713, 2017). "Together, findings provide evidence to support an important role of NRG1 in neurodevelopment and susceptibility to schizophrenia." (PMID 28993723, 2017). "Limited human studies on NRG1 in schizophrenia have shown that the structure and biological process of NRG1 is associated with disease susceptibility as well the clinical phenotypes." (PMID 28993723, 2017). "In summary, human studies demonstrated that NRG1 as a schizophrenia-linked candidate gene plays an important role in the pathological process of schizophrenia through its effect on brain function." (PMID 28993723, 2017). "Studies of patients with schizophrenia demonstrated that NRG1-induced AKT phosphorylation is associated with P50 suppression observed in first-episode patients with schizophrenia." (PMID 28993723, 2017). "In this study, the NRG1 gene was mapped to the chromosome 8p locus (8p11-p21), a region linked to schizophrenia." (PMID 27047540, 2016). "These electrophysiological results implicate NRG1-mediated alterations in dopaminergic activities in the schizophrenia-associated behaviours of this model." (PMID 26935991, 2016). "‎For the first time, we showed that the NRG1 SNP (rs2439272 [A/G]) is significantly ‎associated with the risk of schizophrenia in an Iranian population." (PMID 27928246, 2016).
schizophrenia (continued). "Among the top genes, NRG1 (neuregulin-1) is particularly interesting since this gene is involved in many aspects of brain development and it was associated with schizophrenia risk." (PMID 27091189, 2016). "In human prefrontal cortex, NRG1 stimulation causes a stronger suppression of NMDAR activation in patients with schizophrenia, due to an enhanced interaction between ErbB4 and PSD-95." (PMID 27630777, 2016). "Decreased levels of NRG-1 and its receptor ErbB4 are observed in prefrontal cortex of patients with schizophrenia and the NRG-1 gene has been identified as a leading susceptibility locus for schizophrenia." (PMID 27057274, 2016). "Neuregulin-1 (NRG1), a growth factor genetically linked to schizophrenia in humans, promotes rapid internalization of NMDARs from the cell surface by a clathrin-dependent mechanism in prefrontal pyramidal neurons." (PMID 27630777, 2016). "Interaction between the genes encoding the proinflammatory cytokine interleukin 1β (IL-1β) and NRG1 genotype increases the risk of schizophrenia and shortens the age of onset for the disorder." (PMID 27725886, 2016). "Neuregulin-1 (NRG1) is putative risk gene which has been widely studied in relation to its association with schizophrenia." (PMID 27725886, 2016). "NRG-1 has been identified as a schizophrenia susceptibility gene, and a risk factor for breast cancer and cardiac hypertrophy." (PMID 27918433, 2016). "Aberrant neuregulin-1 (NRG1) signals are suggested to associate with the neuropathophysiology of schizophrenia." (PMID 26935991, 2016). "NRG1-ErbB4 signalling has been intensively studied since the respective genes encoding these proteins were identified as schizophrenia susceptibility genes." (PMID 27456313, 2016). "One of the mechanisms by which NRG1-ErbB4 signalling regulates these processes is through activation of Kalirin-7, a gene previously implicated in schizophrenia." (PMID 27847649, 2016). "While loss of NRG1-ErbB4 signalling is detrimental, excessive NRG1-ErbB4 activity (as seen in schizophrenia) is also associated with synaptic dysfunction resulting from suppression of LTP-induced NMDA receptor function." (PMID 27456313, 2016). "Neuregulin 1 (Nrg1) is a candidate schizophrenia risk gene which has been found to increase GluN2B phosphorylation via PLCγ-dependent mechanism in cortical neurons." (PMID 27134685, 2016). "NRG1 function is mediated by a class of receptor tyrosine kinases including erbB4, and has been shown to associate with schizophrenia with altered NRG1/erbB4 signaling being reported in the brains of schizophrenia patients." (PMID 27895608, 2016). "Two susceptibility factors for schizophrenia, NRG1 and DISC1, have been demonstrated to be linked by a common pathway involving PI3K/Akt." (PMID 26877878, 2016). "Variants in the gene coding for Neuregulin 1 (NRG1) have also been strongly associated with increased risk for schizophrenia." (PMID 26858612, 2015). "The susceptibility genes for schizophrenia Neuregulin-1 (NRG1) and ErbB4 have critical functions during brain development and in the adult." (PMID 26733804, 2015). "The genes encoding NRG1, ErbB3, and ErbB4 have been identified as susceptibility genes for schizophrenia, and a disruption in the ErbB4 gene has been described in schizophrenic patients." (PMID 26733804, 2015). "The gain and loss of function of Nrg1/ErbB4 signaling were examined because postmortem studies of schizophrenia reported both increased and decreased NRG1/ERBB4 signaling in schizophrenic patients." (PMID 25805966, 2015). "Nrg1 TM HET mice show behavioural features relevant to the symptoms of schizophrenia and display altered susceptibility to the neurobehavioural effects of cannabinoids and other psychoactive drugs." (PMID 25992564, 2015). "Our results are consistent with these lines of evidence, which indicate that upregulation of NRG1-ErbB4 signalling underlies mechanisms relevant to schizophrenia." (PMID 26656849, 2015).
schizophrenia (continued). "Most of schizophrenia-associated single nucleotide polymorphisms (SNPs) in NRG1 are localized in the 5′ and 3′ region of the gene." (PMID 25805966, 2015). "ErbB2/B4 receptors and their ligand neuregulin-1 (NRG1) are encoded by candidate susceptibility genes for schizophrenia." (PMID 24980976, 2014). "For example, genetic association studies have identified the EGF and NRG1 genes as candidates that confer risk for schizophrenia with an A61G single nucleotide polymorphism in the EGF gene associated with early disease onset in male patients." (PMID 24552586, 2014). "An in vitro study also indicated that NRG1 signaling is associated with schizophrenia via the PI3K/AKT-dependent pathway." (PMID 25688191, 2014). "The association between NRG1 and schizophrenia was initially revealed in a study of families in Iceland, and the association has been further confirmed in other ethnic groups." (PMID 24782733, 2014). "NRG3 is a neurotrophic factor, a specific ligand for the receptor tyrosine kinase ErbB4 and a paralog of the growth factor NRG1, all of which are strong candidate risk genes for schizophrenia." (PMID 25093331, 2014). "NRG1 rs35753505 nevertheless has the great advantage that it is one of the first SNPs that has been shown to be associated with schizophrenia, and, therefore, studies have repeatedly aimed to elucidate the biological functions of both NRG1 and rs35753505." (PMID 24683514, 2014). "Among them, Neuregulin 1 and Neuregulin 3 have been reported to contribute to an increased risk for developing schizophrenia." (PMID 24976857, 2014). "In particular, polymorphisms in Neuregulin 1 (NRG1) have been consistently linked to schizophrenia in different populations." (PMID 24891237, 2014). "DISC1 and neuregulin 1 transcend the traditional dichotomy in psychiatric diagnosis, demonstrating susceptibility for an affective spectrum of psychosis from schizophrenia to bipolar disorder and even major depression (St." (PMID 25566074, 2014). "Dysfunction in NRG1 signaling pathways has been implicated in the pathophysiology of a variety of neuropsychiatric diseases including schizophrenia." (PMID 25505409, 2014). "Human studies have shown that a NRG1 polymorphism interacted with psychosocial stress to effect reactivity to expressed emotions in schizophrenia patients and that polymorphic variation in NRG1 interacts with job strain to increase the risk of heart disease." (PMID 25324742, 2014). "One gene that has repeatedly been implicated in schizophrenia is neuregulin 1 (NRG1), which encodes a signalling protein with more than thirty different variants." (PMID 24891237, 2014). "We have recently shown that partial genetic deletion of the schizophrenia susceptibility gene neuregulin 1 (Nrg1) and adolescent stress interact to disturb sensorimotor gating, neuroendocrine activity and dendritic morphology in mice." (PMID 25324742, 2014). "The neurotrophic factor neuregulin 1 (NRG1), is a widely accepted schizophrenia susceptibility gene which plays a significant role in normal brain maturation by influencing neuronal migration, myelination, and synaptic plasticity." (PMID 25324742, 2014). "NRG1 was initially implicated in schizophrenia by a study in an Icelandic sample, and association analyses across 8p21-22 revealed highly significant associations." (PMID 25688191, 2014). "A postmortem study indicates the upregulation of NRG1 expression, while an analysis of patients' blood suggests the downregulation of NRG1 expression that associates with schizophrenia and the risk SNP." (PMID 24949465, 2014). "Neuregulin 1 is a gene implicated in schizophrenia that influences synaptic plasticity via multiple pathways, including those involving NMDAGluRs." (PMID 24391602, 2013). "Neuregulin 1 (NRG1) is linked to an increased risk of developing schizophrenia and cannabis dependence." (PMID 23447498, 2013).
schizophrenia (continued). "Linkage studies in the 1990s and early 2000s originally highlighted the cytogenic region containing the NRG1 gene, 8p22-21, as a possible ‘schizophrenia susceptibility locus’ (SSL)." (PMID 23680237, 2013). "The studies that have showed an association between NRG1 and schizophrenia risk mainly focused on two genomic regions, region A (HapICE) and region B (32,600,000 bp–32,800,000 bp)." (PMID 23301017, 2013). "Nrg1 deficiency also modulated the effects of adolescent THC on neurotransmitter systems involved in the pathophysiology of schizophrenia." (PMID 23447438, 2013). "In this study, we utilized a haplotype-based approach to systematically screen for novel associations, as well as to validate the previously reported variations within ERBB4 and NRG1 that conferred risk of developing schizophrenia." (PMID 23301017, 2013). "NRG1 variants have been associated with dysfunction in a number of schizophrenia-relevant “endophenotypes” including sensorimotor gating as measured by prepulse inhibition of startle (PPI) and working memory." (PMID 23447498, 2013). "These initial findings spurred more than 60 additional studies of NRG1 as a putative schizophrenia risk gene, yielding mixed findings." (PMID 23680237, 2013). "Neuregulin 1 (NRG1) is one of the more promising schizophrenia candidate genes as associations with schizophrenia have been found in several studies." (PMID 23447438, 2013). "Social defeat stress models aspect of psychosocial stress in humans, which has been found to interact with a single nucleotide polymorphism of NRG1 to affect the reactivity of schizophrenia patients to expressed emotion." (PMID 23966917, 2013). "Several studies have investigated the impact of single nucleotide polymorphisms (SNPs) and haplotypes of ERBB4 and NRG1 on the risk of developing schizophrenia." (PMID 23301017, 2013). "Disordered neurotransmission is involved in the pathophysiology of schizophrenia and NRG1, a schizophrenia susceptibility gene, regulates neurotransmitter receptor expression and synaptic plasticity." (PMID 23447498, 2013). "Research was initially focused on NRG1, which was first identified as a susceptibility gene for schizophrenia in an Icelandic population, and then confirmed as a susceptibility gene in an unrelated Scottish population." (PMID 23618463, 2013). "Our laboratory previously identified a novel missense polymorphism (V>L) in the transmembrane region of NRG1 that is associated with schizophrenia." (PMID 22590542, 2012). "Among these genes were ERBB4 and NRG1, providing further support for a role of these genes in schizophrenia susceptibility." (PMID 22253750, 2012). "Schizophrenia patients who carried 3 NRG1/ERBB4/AKT risk genotypes were disproportionately worse in dorsolateral prefrontal function in the image study." (PMID 22558359, 2012). "Neuregulin 1 (NRG1) is a key candidate susceptibility gene for both schizophrenia (SCZ) and bipolar disorder (BPD)." (PMID 22590542, 2012). "Catechol-o-methyl transferase (COMT), brain-derived neurotrophic factor (BDNF), and neuregulin 1 (NRG1) have all been implicated in the pathophysiology of schizophrenia and bipolar disorder (BD)." (PMID 24278715, 2012). "Although ERBB4 has been far less studied than NRG1,preliminary evidence suggests a possible association with schizophrenia." (PMID 21637803, 2011). "Neuregulin-1 is a trophic factor crucial for brain development that is encoded by a schizophrenia susceptibility gene and is highly expressed during late developmental periods and in adulthood." (PMID 21904685, 2011). "Several studies in different populations havepositively reported the association of NRG1 polymorphismswith schizophrenia." (PMID 23508206, 2011). "It is worth mentioning thatthe association of NRG1 with schizophrenia ina demographically distinct population would becompelling evidence in favor of a true associationbetween them." (PMID 23508206, 2011).